TNF (tumor necrosis factor)
Diseases named in the same sentence as TNF in open-access papers (continued):
Sharing a sentence is not in itself a finding about the gene and the disease.
Obesity (continued). "Obesity is considered a low-grade chronic inflammatory status with the increased secretion of pro-inflammatory cytokines from adipocytes, including IL-6 and TNFα." (PMID 37185433, 2023). "TNF is recognized as a classical regulator that synergistically mediates signaling to drive inflammation and is critical for the advancement of obesity." (PMID 37764698, 2023). "Inflammatory biomarkers including hs‐CRP, IL‐6, IL‐4, IL‐1B, IL‐10, and TNF‐α have also been shown to be connected with obesity, diabetes, and CVD." (PMID 36911829, 2023). "Reductions in body weight have been shown to lower circulating levels of TNF-alpha in adults with obesity." (PMID 37139450, 2023). "Inflammation has been regarded as a critical mechanism of cognitive dysfunction in human and animal models of obesity, evidenced by the accumulation of proinflammatory cytokines (TNF-α, IL-1β, and IL-6)." (PMID 36334250, 2023). "TNF-α participates in the apoptosis and atrophy of brown adipocytes induced by insulin resistance and promotes the development of obesity with hyperinsulinemia." (PMID 37693249, 2023). "We next examined if obesity affected the production of psoriasis-related proinflammatory cytokines IL-6 and TNF-α in the serum after imiquimod treatment." (PMID 36982669, 2023). "Usually, pregnant women with obesity at pre-pregnancy or becoming obese have a lipotoxic placental environment leading to increased OS and elevated concentrations of TNF-α, IL-1, IL-1β, IL-3, IL-4 and IL-6, and IFN-γ." (PMID 37891973, 2023). "In obesity, adipose tissue-resident macrophages change their phenotype from M2 toward M1, which increases the production of pro-inflammatory cytokines, such as tumor necrosis factor (TNF)-α." (PMID 37048349, 2023). "In studies about obesity, fatty acids, and TNF have been shown to induce M1 polarization along with obesity-induced hypoxia." (PMID 37047082, 2023). "Individuals with both obesity and vitamin D insufficiency exhibit elevated levels of proinflammatory cytokines, such as IL-6 and TNFα (tumor necrosis factor α)." (PMID 38276294, 2023). "Obesity is associated with low-grade systemic inflammation and increased levels of inflammatory markers such as the toll-like receptor 4 (TLR4), tumor necrosis factor-alpha (TNF-α), and IL-6." (PMID 37056543, 2023). "In obesity, oxidative stress, along with the release of pro-inflammatory cytokines, such as leptin, IL-6, and TNF-α from adipose tissue, can lead to NAFLD, non-alcoholic steatohepatitis, fibrosis, and liver cirrhosis progression." (PMID 37246210, 2023). "Adipocytes secrete several pro-inflammatory mediators and among them, TNF-α has been proposed to develop a link between IR, obesity and T2DM." (PMID 37013538, 2023). "On the other hand, we found a significant positive correlation between histone acetylation levels and TNF-α, proposing histone hyperacetylation as a contributing factor in the low-grade inflammation that is commonly observed in obesity." (PMID 37862340, 2023). "Only one study observed significantly decreased levels of TNF‐α and leptin and increased adiponectin concentration in the HIIT group, which has been associated with a lower risk of obesity and breast cancer mortality." (PMID 37587859, 2023). "Obesity constitutes of overproduction of inflammatory cytokines such as tumour necrosis factor-a (TNF-α), and interleukin (IL)- 1,6 and 8 in adipocytes, which is directly related to the pathogenesis of psoriasis." (PMID 40802721, 2023). "The correlation between TNF-α, IL-6, and their involvement in obesity and metabolic disorders is well-established." (PMID 37919772, 2023). "The immune system is not only coordinated by inflammatory stimuli, such as TNF released from adipocytes during obesity but also through neuro-endocrine factors, for example, glucocorticoids (GCs)." (PMID 37080971, 2023).
Obesity (continued). "The state of inflammation in HDV-RNA+ patients is similar to the systemic inflammatory milieu in obesity (i.e., enhanced TNF levels and also conversion of memory T cells to naïve T cell subsets)." (PMID 37877022, 2023). "Inflammatory cytokines, including interleukin (IL)-6, tumor necrosis factor alpha (TNFα), and IL-1β, have been shown promote the expansion of myeloid progenitor cells and are produced by both adipocytes and macrophages in obesity." (PMID 38041006, 2023). "MLKL, which can directly induce necroptosis, has been reported to be involved in different inflammatory diseases, including tumor necrosis factor-induced shock, ischemia–reperfusion injuries, and obesity." (PMID 37924005, 2023). "Inflammatory markers, including C-reactive protein, interleukin-6, and tumor necrosis factor, are positively related to obesity and the aggravation of insulin resistance." (PMID 36803382, 2023). "TNFα is significant in a conversation about obesity because it is produced and secreted by adipose tissue; studies have shown that in obese mice TNFα is overexpressed." (PMID 36078455, 2022). "TNF-α, which was the first identified co-effector of inflammation and obesity, is involved in PA-induced regulation of inflammatory factors and insulin resistance." (PMID 35807921, 2022). "A study on male mice has shown that metformin can attenuate obesity-related asthma by inhibiting the TNF-α-induced inflammatory signaling and NF-κB-mediated iNOS expression in lung tissues." (PMID 36051916, 2022). "Compared with the control group, the level of anti-inflammatory factor IL-10 in the cord blood was decreased in the obesity group, while the levels of proinflammatory factors TNF-α, IL-6, and LPS were increased." (PMID 35600958, 2022). "TNF-α is also continuously expressed by adipose tissue, overexpressed in obesity, and acts as a potential mediator of insulin resistance in several animal models." (PMID 36013196, 2022). "Previous studies have indicated that TNF-α is the key inducer of the well-defined features of MS, such as obesity, impaired glucose utilization, IR, dyslipidemia, and hepatotoxicity." (PMID 36418417, 2022). "Inflammation and adipocyte-derived factors including TNF-α and IL-6 have been reported to link obesity to T2DM." (PMID 36012215, 2022). "Overall, the data included in this section show weak evidence of the reducing effects on body weight and TNF-α of the tested anti-obesity drugs." (PMID 36010524, 2022). "We collected and analysed several human studies where the participants were treated with some of these anti-obesity drugs, and changes in body weight and in the levels of TNF-α were reported." (PMID 36010524, 2022). "Thus, obesity may cause kidney damage by promoting the production of IL-6 and TNF-α." (PMID 35054932, 2022). "Researchers indicated that obesity should play a vital role in the increased secretion of cytokines such as IL-1, IL-6, IL-8, TNF-α, and CRP, and further lead to chronic low-grade inflammation." (PMID 36613000, 2022). "Apparently, inflammatory cytokines are able to induce IR in both adipose tissue and muscle.in case of obesity, adipocytes produce plenty of cytokines such as TNF-α and IL-6, the primary stimulator of the production of CRP in the liver." (PMID 35318405, 2022). "There is a chronic low-grade inflammation developing in obesity, mediated by inflammatory cytokines such as tumor necrosis factor-alpha (TNF-α), interleukin 6 (IL-6), monocyte chemoattractant protein-1 (MCP-1), and interleukin 8 (IL-8)." (PMID 36003642, 2022). "The inflammatory response triggered in the obesity-related kidney injury or in the diabetic nephropathy by NF-κB includes a significant increase of proinflammatory markers in renal tissue, such as TNFα and MCP-1." (PMID 35954150, 2022). "Adults with obesity have been found to have elevated serum levels of TNF-α, and this positively correlates with the development of type 2 diabetes." (PMID 36292751, 2022).
Obesity (continued). "Evidence shows that RES can mediate obesity by inhibiting the activity of NF-κB and suppressing TNF-α through nicotinamide adenine dinucleotide (NAD)-dependent protein deacetylase sirtuin-1 (SIRT1) activation." (PMID 35164043, 2022). "TNF became characterized as an adipokine following the accidental discovery of its enhanced synthesis in adipose tissue in obesity, which led to an understanding of the inflammatory nature of obesity and accompanying metabolic disorders." (PMID 36282842, 2022). "We evaluated the effects of several dietary oils on body weight, fat mass, liver weight, and tumor necrosis factor in obese mice given a high-fat diet (HFD) to discover if coix seed oil (CSO) had an anti-obesity impact." (PMID 37431015, 2022). "On the contrary, plasmatic TNF-α and IL-6 levels decreased after aerobic exercise in children with obesity and overweight." (PMID 36364954, 2022). "TNFα, another important inflammatory cytokine released by adipose stromal cells, including ASCs/MSCs, was increased in the TME of patients with obesity, causing adipose tissue inflammation and inhibiting apoptosis of TNBC cells." (PMID 36010901, 2022). "Obesity-induced hyperleptinemia stimulates the production of pro-inflammatory cytokines such as TNF-α, IL-6, IL-2, IL-1β, and interferon-γ (IFN-γ) by monocytes and T-helper 1, and also inhibits the production of the anti-inflammatory cytokine IL-4." (PMID 36499312, 2022). "The level of IL-10 in the obesity group was much lower than that in the control group, while the levels of TNF-α, IL-6, and LPS showed a significant upward trend." (PMID 35600958, 2022). "With the lipid accumulation in adipose tissues during obesity, fat macrophages release inflammatory cytokines, such as TNF-α and IL-6." (PMID 36157449, 2022). "We found that TNF-α secretion from macrophages was similarly supressed by exposure brain extract from each feeding group, independently of diet composition or obesity." (PMID 35079937, 2022). "This nuclear factor modulates the expression of IL-6, TNF-α, and MIP; these cytokines are closely associated with obesity and pathogen responses." (PMID 35682832, 2022). "Taken together, these results confirm the relationships among obesity, inflammation, and insulin resistance, as well as the key role of TNF-α in the development of obesity and insulin resistance." (PMID 35807921, 2022). "With the increase of various inflammatory factors in serum, such as C-reactive protein (CRP), IL-6, and tumor necrosis factor-α (TNF-α), obesity is essentially a chronic low-grade inflammatory state that is difficult to eliminate." (PMID 36105933, 2022). "In a mouse model of obesity, administration of intravenous TNF-α or IL-1β increased the activity of acetyl-CoA carboxylase, an enzyme that plays a role in regulation of lipid synthesis, and also resulted in hyperlipidemia." (PMID 36292751, 2022). "TNF-α is a multifunctional cytokine, and its elevated production leads to the inflammatory nature of obesity." (PMID 35990345, 2022). "Inflammation has been linked to insulin resistance since the early 1990s, when adipose tissue TNF was shown to be increased during obesity and neutralization of TNF improved peripheral glucose uptake." (PMID 35844529, 2022). "Patients with obesity and high PRL (HP) levels displayed reduced blood glucose, total and LDL cholesterol, triglyceride, and TNFα levels than patients with obesity and normal PRL (NP) levels." (PMID 36213259, 2022). "Obesity inhibits the secretion of the anti-inflammatory adiponectin and increases the secretion of adipokines and pro-inflammatory proteins (TNF-α, IL-6, IFNγ, and TGF-β1), which enhance overexpression of MHC-II in the primary adipocytes." (PMID 35205204, 2022).
Obesity (continued). "In obesity, increased production and secretion of a wide range of inflammatory molecules, including tumor necrosis factor (TNF)-α and interleukin-6 (IL-6) was reported in white adipose tissue." (PMID 36452324, 2022). "Most of the TNF produced by adipose tissue (especially in patients with obesity) is from adipose tissue SVF macrophages." (PMID 37990728, 2022). "Given the first described adipokine was TNF-α, a cytokine, the effects of obesity on inflammation, specifically the production of inflammatory cytokines is not an accident." (PMID 35164764, 2022). "Hotamisligil (2010) observed an increase in TNF-α in the adipose tissue of different animal models (db/db) with obesity and diabetes." (PMID 36406408, 2022). "The presence of PCAT represents a specialized local depot that in the context of obesity and insulin resistance, oxidative stress, and inflammation, promotes a rise in pro-inflammatory cytokines, including tumor necrosis factor-alpha and interleukins." (PMID 36451918, 2022). "TNF-α is identified as a potential target to treat insulin resistance in obesity; it is a classic proinflammatory cytokine and induces M1 polarization of macrophages." (PMID 36230963, 2022). "It has been shown that the level of TNF-α in both adipose tissue and serum is elevated in people with obesity and positively correlates with the ceramides content." (PMID 35745168, 2022). "TNF-α, the first identified co-effector of inflammation and obesity, is significantly more elevated in adipose and muscle tissues of obese rats and humans than in their respective non-obese controls." (PMID 35807921, 2022). "A possible mechanism of the associations between obesity and chronic diseases relies on the theory of inflammation and inflammatory markers such as C-reactive protein (CRP), tumor necrosis factor α (TNF-α), and interleukin 6 (IL-6)." (PMID 35501761, 2022). "To identify the molecular linking between TNF-α and leptin under the state of obesity, we firstly investigated the effects of leptin and TNF-α on the GSIS function in INS-1E cells." (PMID 35198097, 2022). "It was shown that the concentration of CRP in the blood is higher in people (prepubertal and adults subjects) with overweight and obesity in relation to people with normal weight, possibly as a result of the production of IL-6 and TNF-alpha by adipose tissue." (PMID 35053667, 2022). "To test the possible role of SIRT6 on TNFα secretion after the onset of chronic inflammation during obesity, we developed a genetic mouse model for inducible SIRT6 deletion in macrophage colony-stimulating factor receptor 1 (Csf1r)–positive macrophages." (PMID 35150745, 2022). "In this study, cooked adzuki bean significantly inhibited body weight gain, reduced serum TG and proinflammatory cytokines (IL-6, TNF-α, and LPS) levels, and alleviated obesity-related hepatic steatosis and liver injury." (PMID 35782919, 2022). "Serum concentrations of TNFα are elevated in individuals with obesity, and macrophages are thought to be the major source of TNFα in obesity." (PMID 35435599, 2022). "In line with the finding that TNFα production and secretion is upregulated in AT from human patients with obesity, these studies highlight the therapeutic potential of targeting TNFα to combat dyslipidemia and insulin resistance in CMS." (PMID 35557517, 2022). "We found that plasma IL-1β, IL-6, IL-8, IL-12, IL-17, IL-21, IL-32, and TNF-α levels were elevated in obese children with NAFLD compared to subjects with simple obesity." (PMID 36530698, 2022). "Furthermore, obesity is associated with a low-grade inflammation status, and adipose tissue can secrete several proinflammatory factors, such as C-reactive protein, tumor necrosis factor-α, and interleukin-6, which may exert crucial functions in the pathogenesis of OPLL or OLF." (PMID 35937605, 2022).
Obesity (continued). "Among them, phenotype group 3, prevalent in patients with obesity and diabetes mellitus, was characterized by systemic inflammation with elevated levels of inflammatory factors, especially TNF-α and renin, and a preferential response to spironolactone." (PMID 36483560, 2022). "In obesity, TNF triggers IL-33-dependent expression of PD-1 on ILC2s and further recruits and activates PD-L1hi M1 macrophages." (PMID 35574038, 2022). "Obesity has been linked to increased production of several cytokines, including C-reactive protein (CRP), tumor necrosis factor alpha (TNF-α), and interleukin-6 (IL-6)." (PMID 35941593, 2022). "The possible implications of this regulation go beyond LPS-mediated acute inflammation, since macrophage-derived TNFα is also a driving force for chronic inflammation, glucose intolerance, and tissue damage during obesity." (PMID 35150745, 2022). "In line with the pro-inflammatory nature of HFD-induced obesity, we observed a significant increase in gene expression of TNFα in the tibias of HFD-fed mice relative to CR- and NC-fed mice." (PMID 35908046, 2022). "TNF-α can participate in insulin resistance-induced brown adipocyte apoptosis and atrophy, and promote the formation of obesity with hyperinsulinemia, and promote the progression of insulin resistance." (PMID 35923203, 2022). "As in protocol I, ex vivo LPS stimulation testing in whole blood showed that eritoran robustly inhibited TNF-α production in individuals with obesity." (PMID 36066991, 2022). "In chronic low-grade inflammation and obesity, leptin stimulates production of IL-6 and TNF-α and reduces adiponectin." (PMID 35008925, 2022). "The first evidence that obesity is connected with inflammation is the discovery that TNF-α is overexpressed and promotes insulin resistance in obese mice." (PMID 35574038, 2022). "FGF21 is strongly influenced, among others, by TNFα, which is known to be upregulated in obesity-induced inflammation." (PMID 36034917, 2022). "Psoriasis as a chronic systemic inflammatory disease that shares pro-inflammatory mechanisms with obesity, including Th1 cytokines [interferon-γ, interleukin (IL)-2, IL-12, and tumor necrosis factor (TNF)-α]." (PMID 35369048, 2022). "In our study, this inflammatory state was evidenced by the high plasma concentrations of TNF-α and IL-6 in untreated animals and even in those treated with a nutritionally adequate diet, in which obesity was induced for 17 weeks with HGLI diet." (PMID 36364929, 2022). "Compared with obese WT mice, ATM from obese IFN-γ−/− mice exhibited reduced TNF-α expression, and the relative frequency of CD11c+ cells was decreased, which has been shown to designate an obesity-specific M1 inflammatory ATM subpopulation." (PMID 36552805, 2022). "The obesity due to the HSF diet caused cardiac inflammation, observed by elevated IL-6 and TNF-α cytokine." (PMID 34636986, 2022). "In this regard, an increased expression of TNF-α, which is a potent regulator of JNKs, has been demonstrated in obese mice connecting a link between obesity and insulin resistance." (PMID 35455066, 2022). "During obesity, neutrophils have high neutrophil elastase, neutrophil alkaline phosphatase, myeloperoxidase, IL-6, IL-1β, IL-12, IL-8, and TNF-α, and low expression of IL-10, which favors activation of M1 macrophages and development of chronic inflammation." (PMID 36230963, 2022). "While comparing TNF-alpha levels among groups of different body composition, the only difference was seen between “increasing sarcopenic obesity” and “increasing muscle mass” subgroups (median 4.15 pg/mL vs. 3.53 pg/mL; p = 0.033)." (PMID 36558477, 2022). "With respect to TNF-α, the highest values were found when both disorders (obesity and caries) were concomitant in the same child, and a statistically significant difference was identified only between obese individuals with and without caries (p < 0.05)." (PMID 35631100, 2022).